STAT3 (signal transducer and activator of transcription 3)
Diseases named in the same sentence as STAT3 in open-access papers (continued):
Sharing a sentence is not in itself a finding about the gene and the disease.
tumor (continued). "Additionally, Jak2 and STAT3 were analyzed to assess the involvement of these molecules in tumor growth suppression." (PMID 26084564, 2015). "Examples of shortcuts that are observed, and are in agreement with known mechanism in literature include the cross-talk between the Jak-STAT and NF-kappaB pathways or STAT3 signaling enabling cross-talk among tumor and immune cells, resulting in an immunosuppressive network." (PMID 25283527, 2015). "STAT3 acts as transcriptional regulator of a variety of tumor-promoting genes." (PMID 28031890, 2015). "The strong correlation of FOXM1 and STAT3 expression could be confirmed in lysates obtained from frozen primary and metastasis tumor material of GEP-NEN patients." (PMID 25797272, 2015). "By engagement of their specific cellular receptors, cytokines such as IL-6 and IL-10 and VEGF activate the JAK2/STAT3 transduction pathway that promotes the transcription of genes encoding for proteins involved in PEL resistance to apoptosis and contributes to tumor survival." (PMID 25695042, 2015). "In the nude mouse lung metastasis model, the STAT3 inhibitor, S3I-201, could inhibit the Fascin expression in tumor tissues." (PMID 25992623, 2015). "The data suggested that indeed S3I-201 could decrease p-STAT3 and its target gene Cyclin D1 and Bcl2 effectively in vivo, which indicate the decrease of tumor size of nude mice using S3I-201 is an on-target effect." (PMID 26556875, 2015). "IL-17 treatment of tumor cells markedly increased p-STAT3 expression as well as GIV expression." (PMID 26524953, 2015). "It is possible that A2B stimulation could enhance IL-10-mediated STAT3 activation in at last some cell types in our tumor model." (PMID 26317647, 2015). "Several lines of evidence also implicate STAT3 in tumor cell invasion, migration and immune evasion as well as the EMT by promoting Rho GTPase-regulated cell migration and regulating the expression of MMPs, E-cadherin, zinc-finger E-box-binding (ZEB) and vimentin, amongst others." (PMID 26125440, 2015). "In addition, previous work in our lab demonstrated that diclofenac inhibits STAT-3 phosphorylation and lactate formation, induces cell cycle arrest at G2/M, and delays tumor growth in an in vivo animal model." (PMID 26485029, 2015). "Thus, STAT3 functions as tumour suppressor by sequestering NF-κB in the cytoplasm and thereby reducing NF-κB-dependent CXCL1 transcription." (PMID 25734337, 2015). "Furthermore, STAT3 selectively induces and maintains a pro-inflammatory microenvironment that further supports tumour progression." (PMID 26186918, 2015). "However, blockage of cytokine IL-6 or TNF-α signaling or inhibition of NF-κB, STAT3, or cyclinD1 expression reduced the average tumor volume (p < 0.05)." (PMID 25823926, 2015). "In addition, we observed an increase in IL-6Rα levels in tumour cells and soluble IL-6R serum levels as well as increased Stat3, IL-6Rα and IL-6 mRNA levels in Ptenpc−/− PCa compared with WT controls." (PMID 26198641, 2015). "Taken together, these observations showed STAT3 blockade decreased tumor growth may through targeting apoptosis and CSCs phenotype in HNSCC xenograft mouse model." (PMID 26556875, 2015). "In addition, STAT3 activation directly promotes survival, proliferation, and differentiation of tumour cells and MDSCs." (PMID 28781374, 2015). "As an explanation for this result, this increase could be due to other known STAT3 activators that could be produced by IL-17 treatment of tumor cells." (PMID 26524953, 2015). "Overall, these findings revealed that STAT3 blockade could delay tumor initiation and progression in de novo spontaneous mice model through reducing cancer stem cells." (PMID 26556875, 2015). "Astaxanthin, which is a non-provitamin A carotenoid predominantly distributed in microalgae, fungi, plants, and sea foods, is found to inhibit the onset of tumor progression by targeting signal transducer and activator of transcription 3 (STAT3)/Janus kinase 2 (JAK-2)." (PMID 26180591, 2015).
tumor (continued). "The role of IL-1RT1 signaling during IL-11-induced STAT3 activation without tumor inducing gp130 mutations was also assessed." (PMID 25528766, 2015). "Previous studies found that glutamine metabolism could promote tumor growth and invasion through STAT3 pathway, a regulator of EMT and aberrantly activated in CRC." (PMID 25947346, 2015). "STAT3 blockade with S3I-201 could significantly reduce the size and number of tumor spheres which indicating the self-renewal or initiation ability when compared with control." (PMID 26556875, 2015). "G-MDSCs promote tumor angiogenesis via secreting Bv8 which is regulated by STAT3 activation." (PMID 26078490, 2015). "Therefore, our finding highlights a novel aspect of STAT3/GIV pathway in the IL-17 promotes tumor angiogenesis of NSCLC." (PMID 26524953, 2015). "Spheres derived from human PCa cells display elevated STAT3 activation with STAT3 knockdown reducing sphere formation, while treatment with a soluble IL-6 receptor fusion protein inhibited STAT3 activation and prevented tumor growth in vivo." (PMID 25595909, 2015). "Indeed, mitochondrial S-P STAT3 is required for tumor transformation mediated by oncogenic RAS, favoring both aerobic glycolysis and ETC activity and increasing ATP abundance." (PMID 26106584, 2015). "Additionally, increased p-STAT3 expression was also significantly interrelated with positive lymph node metastases status and poorer differentiation of tumor cells." (PMID 26024373, 2015). "Furthermore, vascularization as well as macrophage and granulocyte infiltration was reduced in the IL-8/STAT3 double knockdown tumours compared with STAT3 knockdown tumours." (PMID 25734337, 2015). "Signaling transducer and activator 3 (STAT3) and cancer stem cells (CSCs) have garnered huge attention as a therapeutic focus, based on evidence that they may represent an etiologic root of tumor initiation and radio-chemoresistance." (PMID 26556875, 2015). "Selective STAT3 inhibitors are being developed and may play an important role in restraining both tumor growth and suppressive myeloid cell populations." (PMID 26561829, 2015). "We postulated that IL-17 might affect tumor cells’ production of VEGF by activating the STAT3/GIV pathway in tumor cells." (PMID 26524953, 2015). "Consequently, TAK1 is pivotal to induce the c-Kit-mediated activation of IKK2, STAT3/5 in primary- and tumor-mast cells." (PMID 26353931, 2015). "Furthermore, the STAT3 activity in tumor cells enhances the expression of several immune-suppressing soluble factors, such as IL-6, IL-10 and VEGF, all of which are known to prevent the maturation of dendritic cells." (PMID 24995504, 2014). "In addition, STAT3 siRNA inhibits tumor cell growth and proliferation by down-regulating c-Myc and cyclin D1." (PMID 24743778, 2014). "Some tumor cell lines need constitutive activation of STAT3 in order to survive." (PMID 24675568, 2014). "Studies of STAT3-regulated expression of fascin will provide new insight into the mechanisms by which IL-6 promotes GC metastasis, in which multiple factors contribute to the critical step of primary tumor metastasis." (PMID 24527098, 2014). "STAT3 seemingly has many more functions that support tumor growth than to suppress tumor growth." (PMID 24743777, 2014). "Enhanced drive for expression of IL-6 and IL-11 may also be due to increased ligand driven EGFR activation, which also signal via STAT3, and which show increased expression during active tumour growth in the gp130757FF mouse." (PMID 24804649, 2014). "This CCR7/JAK2/STAT3 signal pathway regulates tumor metastasis by E-cadherin-mediated tumor EMT." (PMID 25405202, 2014). "Another example of a gene that is primarily up regulated by STAT3 but may support or suppress tumor growth is JunB." (PMID 24743777, 2014). "Furthermore, p-STAT3 can upregulate the expression of matrix metalloproteinase 2 (MMP2) to promote the formation of VM in tumor tissues." (PMID 24959290, 2014).
tumor (continued). "WP1066 was also effective when given in vivo, where it blocked STAT3 activation (75%) in gp130757FF mouse antral tumours, and also reduced total STAT3 protein, suggesting that it may decrease expression of the Stat3 gene in the stomachs of treated mice." (PMID 24804649, 2014). "Furthermore, the B cells from the normal Balb/c mice were treated with phosphate-buffered saline, JSI124 and 4T1 tumor cells, then the B cell STAT3 levels were analyzed." (PMID 25013518, 2014). "This is further evidence suggesting the cellular context may play a significant role in whether STAT3 up regulates or down regulates genes in which STAT3 has dual regulation and, consequently, whether STAT3 supports or suppresses tumor growth." (PMID 24743777, 2014). "Consequently, suppression of the activity of AP-1, STAT3, or NF-κB binding to respective regulatory elements potentially inhibits tumor invasion." (PMID 24618693, 2014). "A previous study demonstrated that STAT-3, by affecting the differentiation and maturation of dendritic cells (DCs), interfered with immune recognition by T cells and thus, the immune system became tolerant of the tumor cells." (PMID 25009646, 2014). "While STAT3 is clearly an integral pathway to tumor growth and invasion, lifting the “brakes” on immune function through STAT3 checkpoint blockade combined with tumor-specific vaccine therapy may show promise for more robust anti-tumor responses." (PMID 24518612, 2014). "Sustained activation of STAT3 can promote tumor cell survival and migration." (PMID 25268165, 2014). "In summary, our studies revealed that CXCL12/CXCR7-induced STAT3-mediated pathways may enhance tumor growth by regulating angiogenic and proliferative pathways." (PMID 24886617, 2014). "Therefore, investigating the association between STAT3 and VM formation in GAC is worthwhile to learn more about tumor development, invasion and metastasis." (PMID 24959290, 2014). "In other words, accurate evaluation of the biological and clinical significance of STAT3 in human tumor samples will require some understanding of the relevant coexisting biochemical defects (e.g., c-myc, PTEN and p14ARF) as well as the simultaneous evaluation of STAT3α and STAT3β." (PMID 24995504, 2014). "Importantly, Huh7 tumor-bearing nude mice treated with SC-2001 showed downregulation of Mcl-1 and p-STAT3 protein expression and upregulation of SHP-1, LC3II, and RFX-1 protein expression." (PMID 24952874, 2014). "Another report describing the tumor suppressor effects of STAT3 was published in 2011." (PMID 24995504, 2014). "Furthermore, the impact of Stat3 activity in B cells for tumor progression was accompanied by enhanced tumor angiogenesis representing increased numbers of tumor-associated blood vessels." (PMID 24782982, 2014). "Importantly, some of these studies have demonstrated that STAT3 can function either as an oncoprotein or a tumor suppressor in the same cell type, depending on the specific genetic background or presence/absence of specific coexisting biochemical defects." (PMID 24995504, 2014). "However, even in the presence of activated STAT3, other cellular modulators can have a major impact on the biological properties of a cancer cell, which is reflected in the clinical behavior of a tumor." (PMID 24762632, 2014). "STAT3 can, therefore, have effects that both promote and suppress tumor growth." (PMID 24743777, 2014). "Curcumin has been extensive studied for its STAT3-inhibitory properties and anti-tumor activity." (PMID 24675768, 2014). "Furthermore, STAT3 activation in developed tumor cells was decreased by the administration of CA, thus suggesting that CA suppresses STAT3 activation in both in vitro and in vivo models." (PMID 24738052, 2014). "Furthermore, anti-IL-6 antibodies partially abrogated senescent MSC-CM-induced enhancement of tumor cell proliferation, migration and STAT-3 phosphorylation." (PMID 25419563, 2014).
tumor (continued). "As the author speculated, the tumor suppressor function of STAT3 in the carbon tetrachloride model correlates well with the fact STAT3 is known to play an important role in protecting liver against hepatocellular damage." (PMID 24995504, 2014). "However, sorafenib modifies the tumor microenvironment not only through STAT3 pathway, but TGF-β pathway as well." (PMID 25333973, 2014). "Results from promoter mutagenesis and chromatin immunoprecipitation assays further indicated that the VEGF gene is directly regulated by STAT3, thereby suggesting that STAT3-targeted therapy could play a significant role in disrupting tumor neovascularization." (PMID 24518612, 2014). "In addition, we identified IL-6, a known pleiotropic cytokine, as a principal mediator for the tumor-promoting activity of s-UCMSCs by induction of STAT3 phosphorylation." (PMID 25419563, 2014). "There was also enhanced phosphorylation of STAT3 protein (Ser727) in the presence of the C26 tumor." (PMID 24667661, 2014). "Moreover, we found significantly higher STAT3 phosphorylation in high IL-6-producing tumor tissues than that in low IL-6-producing tissues." (PMID 24789104, 2014). "STAT3 has also been shown to have differing effects on tumor growth through regulation of TIMPs." (PMID 24743777, 2014). "Whether sorafenib improves the tumor microenvironment to enhance the function of OT-1 CD8+ T cells through other signal pathways other than STAT3 pathway needs to be further investigated." (PMID 25333973, 2014). "However, there are also a great number of genes that STAT3 regulates that have dual roles in tumor growth." (PMID 24743777, 2014). "In addition to its oncogenic functions, recent studies have attributed STAT3 as a mediator of tumor-induced immunosuppression." (PMID 24806510, 2014). "However, both groups observed a dramatic increase in tumor invasion of Apcmin/+ tumors in the intestines upon deletion of Stat3 in IEC in vivo." (PMID 24995503, 2014). "Here, we summarize the role of STAT3 in various tumor entities and how this knowledge may be used to improve the treatment of CRT-resistant tumors." (PMID 25268165, 2014). "Indeed, the JAK inhibitors INCB16562, AZD1480, and tofacitinib (CP-690550) have potently blocked STAT3 signaling, suppressed cancer cell proliferation, or induced apoptosis in vitro and tumor growth in vivo." (PMID 24662938, 2014). "Indeed, the identity of STAT3 as an oncogene or a tumor suppressor has been questioned in different tumor types." (PMID 24662939, 2014). "We further demonstrate that inhibition of STAT3 by siRNA-mediated knockdown or a small molecule inhibitor S3I-201 universally sensitized trastuzumab-resistant cells to trastuzumab treatment and significantly suppressed tumor growth in vitro and in vivo." (PMID 25327561, 2014). "On the other hand, studies have also shown that STAT3 may paradoxically facilitate tumor suppression by contributing to cell differentiation, growth inhibitory signaling, and apoptosis." (PMID 24518612, 2014). "Thus, the effect of epithelial STAT3 signaling on tumor initiation is likely very different in sporadic CRC versus CAC." (PMID 24995503, 2014). "Moreover, the aberrant activation of STAT3 has been broadly characterized as a regulator of tumorigenesis through its effects in tumor cells, tumor microenvironment, and metastasis." (PMID 24886617, 2014). "Finally, we bring forward the favorable prognostic effect of VEGF expression at the tissue level, as reported in the peripheral blood, as well as of p-STAT-3 positivity consistent with its tumor suppressive effect." (PMID 24883303, 2014).
tumor (continued). "The combination of EGFR with STAT3 inhibitors has shown improved anti-tumor activity in other pre-clinical models; certainly, data from the current study would support further investigation of combining Dacomitinib with a STAT3 inhibitor for SCCHN." (PMID 24853121, 2014). "Therefore the regulation of Th17 development by STAT3 is an example of a family of genes regulated by STAT3 that drive cell development and affect tumor immune function." (PMID 24743777, 2014). "Because IL-28 (IFN-λ) activates STAT3, we decided to explore whether it functions in signaling between MDSCs and tumor cells." (PMID 25075523, 2014). "This raises the possibility that isolated activation of STAT5 would not be oncogenic without the coordinate activation of another signaling molecule, such as STAT3, that could prevent tumor differentiation." (PMID 24762632, 2014). "Moreover, we showed for the first time that MDSCs communicate with tumor cells via IL-28/IL-28RA (IFN-λ) signaling activating STAT3 and thus stimulating angiogenesis, cancer cell EMT, invasion and migration." (PMID 25075523, 2014). "In addition, the direct STAT3 target genes where the outcome is the tumor suppressing functions of STAT3 will be detailed." (PMID 24743777, 2014). "In vitro study, we also observed whether α-Solanine intervened in the Wnt/β-catenin, Akt/mTOR, Stat3 and NF-κB pathways which had a critical influence on tumor cells proliferation, angiogenesis and metastasis." (PMID 24505326, 2014). "Moreover, persistent activation of STAT3 is not limited to the tumor itself: it is also transmitted to stromal inflammatory cells in the tumor microenvironment." (PMID 25149535, 2014). "By using different experimental tumor models they could show that B cells differ in their function in dependence of STAT3 expression." (PMID 24782982, 2014). "The chemokine (C-X-C motif) ligand 1(CXCL1) is co-regulated by the NF-κB and STAT3 signaling, and its overexpression in dysplastic phases suggested that it may function as a tumor initiator." (PMID 25057912, 2014). "Persistent STAT3 signalling could promote the growth and survival of tumor cells, induce tumor angiogenesis and suppress the anti-tumor immune responses." (PMID 25594045, 2014). "Thus, inhibition of STAT3 signaling using siRNAs or pharmacological agents can effectively reduce tumor growth by suppressing the expression of these cell-cycle facilitators." (PMID 24995504, 2014). "Additional evidence suggested that STAT3 may elicit opposing effects depending on cellular context and tumor types." (PMID 24743777, 2014). "Importantly, some of these studies have proposed a novel concept that STAT3 can function as an oncoprotein or tumor suppressor in the same cells, and the decision is dependent on the genetic background and/or coexisting biochemical defects." (PMID 24995504, 2014). "STAT3 upregulation of TIMP-1 provides a clear illustration of a gene up regulated by STAT3 but may support or suppress tumor growth depending on the context in which it is expressed." (PMID 24743777, 2014). "To test the tumor dependence on STAT3, we used shRNA to specifically knock down STAT3." (PMID 25261365, 2014). "Understanding the mechanism of the tumor suppression pathway activated by regorafenib may provide a new therapeutic strategy through which to abolish STAT3 oncogenic signaling." (PMID 25071018, 2014). "Based on a previous study that reported that B cells promote tumor angiogenesis in a STAT3-dependent manner, the present study investigated the function of B cells in 4T1 mice, JSI124-treated 4T1 mice, 4T1-cocultured B cells and JSI124-treated B cells in vitro." (PMID 25013518, 2014). "Similarly PELP1 which interacts directly with STAT3 and is responsible for cell proliferation and survival in several tumours, is likewise an identified drug target in PDAC." (PMID 25521701, 2014). "STAT3 can regulate several tumor suppressing genes in these areas." (PMID 24743777, 2014).